DOCK2 (dedicator of cytokinesis 2)
Diseases named in the same sentence as DOCK2 in open-access papers (continued):
Sharing a sentence is not in itself a finding about the gene and the disease.
melanoma (4 papers, 2021 to 2025). A malignant, usually aggressive tumor composed of atypical, neoplastic melanocytes. "These cell-based data validate our biochemical results and underscore the critical role of DOCK2 in maintaining RAC1P29S-driven oncogenic signaling in melanoma cells." (PMID 41034404, 2025). "Most importantly, we demonstrate that RAC1P29S remains constitutively active in IGR1 human melanoma cells even under serum-starved conditions and that its activation can be significantly reduced by the pharmacological inhibition of DOCK2 with CPYPP." (PMID 41034404, 2025). "The results also suggest that targeting DOCK2 is an effective inhibitory strategy for counteracting RAC1P29S-driven melanoma cell invasion." (PMID 41034404, 2025). "Together, our findings provide direct evidence that RAC1P29S is constitutively active in melanoma cells and that DOCK2-mediated activation contributes to its pathological function." (PMID 41034404, 2025). "Sixth, editing of DOCK2 mRNA enhanced its stability and upregulated the expression of stemness and antiapoptotic genes, which in turn promoted oncogenesis of melanoma stem cells." (PMID 35406793, 2022). "A recent study has revealed that DOCK2 plays an important role in the malignant development of tumors by regulating melanoma stem cell activity." (PMID 36250020, 2022). "Overall, DOCK2 promotes the proliferation of melanoma stem cells and inhibits stem cell apoptosis, thus promoting the development, metastasis, and recurrence of melanoma." (PMID 36250020, 2022). "Furthermore, pharmacological inhibition of DOCK2 with CPYPP significantly reduced RAC1P29S activation, establishing DOCK2 as a pivotal upstream activator in melanoma." (PMID 41034404, 2025). "Furthermore, DOCK2 inhibition using CPYPP significantly reduced RAC1P29S activity in a dose-dependent manner, which supports the central role of DOCK2 as the primary GEF responsible for RAC1P29S activation in melanoma cells." (PMID 41034404, 2025). "This evidence positions DOCK2 as the primary potential activator of RAC1P29S in cancer cells, particularly in melanoma." (PMID 41034404, 2025). "Taken together, our findings identify RAC1P29S as a constitutively active mutant and highlight DOCK2, p50GAP, and IQGAP1 as potential therapeutic targets for suppressing RAC1P29S-driven melanoma progression." (PMID 41034404, 2025). "Another study also confirmed that DOCK2 is regulated by the hnRNP A2B1 variable shedder, thus promoting the malignant development of melanoma by helping melanoma stem cells evade the normal apoptotic process in vivo and in vitro." (PMID 36250020, 2022). "Therefore, DOCK2 could be a candidate target for the clinical treatment of melanoma." (PMID 36250020, 2022). "In this study, the results showed that hnRNP A2B1 suppressed apoptosis of melanoma stem cells through post-transcriptional regulation of apoptosis-related DAPK1, SYT7, RNF128, EIF3H, TPPP3, and DOCK2 genes." (PMID 33509274, 2021). "On the other hand, the hnRNP A2B1 overexpression resulted in significant upregulations of TPPP3, EIF3H, and DOCK2 and downregulations of DAPK1, RNF128, and SYT7 in melanoma stem cells." (PMID 33509274, 2021). "Western blot data indicated that the hnRNP A2B1 silencing led to significant downregulations of TPPP3, EIF3H, and DOCK2 and upregulations of DAPK1, RNF128, and SYT7 in melanoma stem cells compared with the control." (PMID 33509274, 2021). "Taken together, these findings revealed that hnRNP A2B1 played a positive role in tumorigenesis of melanoma stem cells in vivo by affecting the splicing of TPPP3, DOCK2, EIF3H, RNF128, DAPK1, and SYT7, thus suppressing apoptosis of melanoma stem cells." (PMID 33509274, 2021). "Our findings revealed that the hnRNP A2B1-mediated splicing triggered the upregulation of TPPP3, DOCK2, and EIF3H, and the downregulation of RNF128, DAPK1, and SYT7 in melanoma stem cells, leading to the suppression of apoptosis of cancer stem cells." (PMID 33509274, 2021).
melanoma (continued). "The in vivo data indicated that hnRNP A2B1 was required for tumorigenesis by affecting the splicing of TPPP3, DOCK2, EIF3H, RNF128, DAPK1, and SYT7, thus suppressing apoptosis of melanoma stem cells." (PMID 33509274, 2021). "Together, these results imply that targeting upstream regulators such as DOCK2 and downstream effectors, such as IQGAP1, could be effective therapeutic strategies for counteracting RAC1P29S-mediated melanoma progression and resistance to targeted therapies." (PMID 41034404, 2025). "Collectively, it could be concluded that hnRNP A2B1 promoted tumorigenesis of melanoma stem cells via regulating the splicing of the precursor mRNAs of TPPP3, DOCK2, EIF3H, RNF128, DAPK1, and SYT7." (PMID 33509274, 2021). "Northern blot data indicated that TPPP3, DOCK2, and EIF3H were significantly upregulated in melanoma stem cells compared with cancer non-stem cells, while RNF128, DAPK1, and SYT7 were downregulated in melanoma stem cells." (PMID 33509274, 2021).
pneumonia (4 papers, 2022 to 2023). An acute, acute and chronic, or chronic inflammation focally or diffusely affecting the lung parenchyma, caused by an infection in one or both of the lungs (by bacteria, viruses, fungi, or mycoplasma.). "In a Syrian hamster model of SARS-CoV-2 infection, inhibition of DOCK2 expression with CPYPP resulted in worsening of pneumonia characterized by weight loss, pulmonary edema, increased viral load, impaired macrophage recruitment, and dysregulation of the type I IFNs response." (PMID 36250020, 2022). "Moreover, inhibition of DOCK2 function with CPYPP increased the severity of pneumonia in a Syrian hamster model of SARS-CoV-2 infection, characterized by weight loss, lung oedema, enhanced viral loads, impaired macrophage recruitment and dysregulated type I interferon responses." (PMID 35940203, 2022).
pulmonary fibrosis (4 papers, 2022 to 2025). Chronic progressive interstitial lung disorder characterized by the replacement of the lung tissue by connective tissue, leading to progressive dyspnea, respiratory failure, or right heart failure. "Researchers have reported that DOCK2 plays an important role in fibroblasts and influences in the development and progression of pulmonary fibrosis." (PMID 36250020, 2022). "The alteration of TNF-α-induced, lung fibroblast (LF) pro-inflammatory phenotype in high-fat and high-fructose (HFHF)-induced pulmonary fibrosis was found to be possibly mediated by DOCK2-regulated PI3K/AKT and NF-κB pathways." (PMID 36250020, 2022). "The involvement of DOCK2 in the transition of lung fibroblast (LF) phenotype affecting lung disease was also confirmed in a bleomycin-induced lung fibrosis model in mice and in IPF patients." (PMID 36250020, 2022). "The researchers also found that DOCK2 mediates fibroblast to myofibroblast transition (FMT) in the development of idiopathic pulmonary fibrosis (IPF)." (PMID 36250020, 2022). "A recent study showed that high-fat and high-fructose diet could facilitate lung fibrosis through inducing lung fibroblasts inflammation via transcriptional up-regulating dedicator of cytokinesis 2 (DOCK2)." (PMID 36979493, 2023). "DOCK-2 is induced by TGF-β and contributes to fibrosis in idiopathic pulmonary fibrosis." (PMID 40475059, 2025). "DOCK2 promotes pleural fibrosis by regulating the mesothelial to mesenchymal transition (MesoMT) leading to restrictive lung disease, as well as mediating the transition of fibroblasts to myofibroblasts (FMT) during the development of idiopathic pulmonary fibrosis (IPF)." (PMID 36250020, 2022).
colon cancer (3 papers, 2021 to 2024). "Vil Apc Dock2 mice developed more colonic tumours than controls and had an increased overall tumour burden." (PMID 39242821, 2024). "Furthermore, cholesterol sulfate inhibits dedicator of cytokinesis protein 2 (DOCK2), a Rac activator crucial for lymphocyte activation and migration, decreasing CD8+ T cell infiltration into colon cancer tissues." (PMID 39280099, 2024).
combined immunodeficiency (3 papers, 2021 to 2025). A broad classification of inherited disorders presenting at birth that affect both the cell-mediated and humoral aspects of the immune response. "Biallelic loss-of-function mutations in the DOCK2 gene are associated with clinical features of combined immunodeficiency (CID) according to the primary immunodeficiency (PID) treatment consortium (PIDTC)." (PMID 34872585, 2021). "On one hand, an impaired formation of the immune synapse reflects on reduced cooperation between immune cells and defective lymphocyte activation and cytotoxic function, leading to more or less severe combined immunodeficiency, as in DOCK2, DOCK8, Coronin 1, and WIP deficiencies." (PMID 33809703, 2021).
non-small cell lung carcinoma (3 papers, 2022 to 2023). A group of at least three distinct histological types of lung cancer, including non-small cell squamous cell carcinoma, adenocarcinoma, and large cell carcinoma. "Moreover, the DOCK2 genetic variant caused decreased DOCK2 mRNA transcript levels and might be a prognostic biomarker of non-small-cell lung cancer survival." (PMID 35620462, 2022). "Furthermore, down-regulation of DOCK2 may contribute to the development of non-small cell lung cancer and affect prognostic adverse effects through the activation of the MYC and DNA repair signaling pathways." (PMID 36250020, 2022). "For example, DOCK2 is upregulated in follicular lymphoma and downregulated in NSCLC (non-small cell lung cancer)." (PMID 37027440, 2023).
Obesity (3 papers, 2018 to 2023). Accumulation of substantial excess body fat. "Dock2 and Inpp5d, which exhibit an affected binding of miR-29b are involved in chemokine signaling and Fc gamma R-mediated phagocytose, thus, in pathways known to associate obesity with insulin resistance." (PMID 32350386, 2020). "A recent experimental study indicated that DOCK2 deficiency might protect mice from high-fat-diet induced obesity by reducing adipose tissue inflammation and increasing energy expenditure." (PMID 29868124, 2018). "In mouse obesity models, DOCK2 signaling is increased in lung tissue, concentrated in resident lung fibroblasts." (PMID 37759429, 2023).
B-cell lymphoma (2 papers, 2021 to 2022). "In addition, a study showed that DOCK2-Rac-ERK pathway is associated with cell proliferation of B-cell lymphoma cell lines Ramos and Raji." (PMID 36250020, 2022). "In lymphocytes, downregulation of DOCK2 expression using sh-RNA leads to decreased proliferation of B-cell lymphoma cells, a mechanism related to DOCK2-mediated Rac-ERK." (PMID 36250020, 2022).
bacterial sepsis (2 papers, 2023 to 2025). "For this child with a DOCK2 missense mutation, it was likely repeated episodes of bacterial sepsis that served as the triggering events." (PMID 36836791, 2023). "Our data indicates that DOCK2 acts as a protective role in regulating systemic inflammation and multi-organ injury in bacterial sepsis by constraining Th1 response." (PMID 40510337, 2025). "In this work, we identified an essential role for DOCK2 in bacterial sepsis." (PMID 40510337, 2025).
follicular lymphoma (2 papers, 2019 to 2023). Follicular lymphoma is a form of non-Hodgkin lymphoma characterized by a proliferation of B cells whose nodular structure of follicular architecture is preserved. "Previous study found that DOCK2 plays a key role in the regulation of cell proliferation in diffuse large B cell lymphoma and follicular lymphoma via the ERK signaling pathway." (PMID 31762818, 2019).
injury (2 papers, 2022 to 2025). Damage inflicted on the body as the direct or indirect result of an external force, with or without disruption of structural continuity. "DOCK2 inhibition may inhibit LPS-induced macrophage activation and may be a novel target for the treatment of endotoxemia-associated acute lung injury." (PMID 36250020, 2022). "In another model of acute lung injury (ALI),LPS induced DOCK2 expression and reached its highest potent in the most severe lung injury." (PMID 36250020, 2022).
rheumatoid arthritis (2 papers, 2018 to 2021). A chronic, systemic autoimmune disorder characterized by inflammation in the synovial membranes and articular surfaces. "DOCK2 signaling has been linked to synovitis associated with rheumatoid arthritis in human beings." (PMID 29940858, 2018).
actinopathies (1 paper, 2021). "In conclusion, a number of actinopathies are associated with alterations in the homing of lymphocytes and DCs to LNs (WASP, DOCK2, STK4/MST1) and/or in the egress of antigen-experienced lymphocytes from LNs (DOCK2, MSN, STK4/MST1)." (PMID 34867982, 2021).
Allergy (1 paper, 2022). An allergy is an immune response or reaction to substances that are usually not harmful. "DOCK2 is critically involved in the development of several inflammatory diseases, including allergy, graft rejection and even human immunodeficiency virus infection." (PMID 36380073, 2022).
autism spectrum disorder (1 paper, 2018). A spectrum of developmental disorders that includes autism, and Asperger syndrome. "Based on GSEA, correlation, and PPI analysis, we conclude that DOCK2 acts as a molecular hub for channelized signaling in microglia-based neuroprotection, neuroinflammation, and neurological diseases, including AD and PD, Autism spectrum disorders, and schizophrenia." (PMID 29755398, 2018).
breast carcinoma (1 paper, 2020). "CD1B (CD1b molecule), THY1 and DOCK2 (dedicator of cytokinesis 2) were found to be implicated in the metastatic recurrence of breast cancer." (PMID 32867782, 2020). "High expression of THY1 was more likely to cause metastasis of breast cancer, while low expression of CD1B and DOCK2 was likely to cause metastasis of breast cancer." (PMID 32867782, 2020). "Among the key genes, ASPN, DOCK2, THY1 and KYNU were found to be associated with breast cancer based on NCBI Entrez database." (PMID 32867782, 2020). "Together with our results, we speculated that DOCK2 may be a prognostic marker of metastatic recurrence in breast cancer." (PMID 32867782, 2020). "THY1 and NEU2 may be potential therapeutic targets for breast cancer with brain metastases, and THY1, CD1B and DOCK2 may serve as potential prognostic markers for improvement of brain metastases survival." (PMID 32867782, 2020).
Cerebral ischemia (1 paper, 2022). Restriction of arterial blood supply to the brain associated with insufficient oxygenation to support the metabolic requirements of the tissue. "DOCK2 has also been shown to have an important role in cerebral ischemia/reperfusion." (PMID 36250020, 2022). "It was demonstrated that DOCK2 promotes the involvement of M1 microglia in the inflammatory response by affecting p-STAT6, which promotes the development of cerebral ischemia/reperfusion." (PMID 36250020, 2022).
colorectal adenocarcinoma (1 paper, 2022). The most common type of colorectal carcinoma. "Whole genome sequencing of cancer tissues from patients with esophageal and colorectal adenocarcinoma revealed high-frequency mutations in DOCK2, suggesting that DOCK2 may play an important role in maintaining mucosal homeostasis." (PMID 36250020, 2022).
coronary artery stenosis (1 paper, 2021). "The analysis showed that apolipoprotein C-II (APOC2), dedicator of cytokinesis protein 2 (DOCK2), ligand 7 (CXCL7) and vitamin D binding protein (VTDB) were activated, and complement 4A (C4A) were suppressed in diabetic patients and were associated with severe coronary artery stenosis." (PMID 34948066, 2021).
depression (1 paper, 2024). "Of 10 GWAS studies of MDD or depression, two found an association between DOCK2 and MDD/depression, and four indicated loci in UGT8, PTPRM, or DAB1 as variants associated with MDD/depression." (PMID 39287932, 2024).
dermatitis (1 paper, 2025). An inflammatory process affecting the skin. "However, if only the SULT2B1-CS-DOCK2 axis is affected in psoriasis-like dermatitis, psoriatic phenotypes in Sult2b1−/−Dock2−/− mice would be expected to decrease to WT levels." (PMID 41181147, 2025). "Furthermore, genetic deletion of Dock2 or intravenous administration of neutrophil-depleting antibodies alleviated IMQ-induced dermatitis in Sult2b1 knockout mice." (PMID 41181147, 2025).
E. coli infection (1 paper, 2025). "Expectedly, we observed impaired survival of Dock2−/− mice when compared to with WT animals within 72 h of E. coli infection." (PMID 40510337, 2025). "In addition, we found that the deficiency of DOCK2 significantly augmented the frequencies and numbers of CD4+IFN-γ+ inflammatory Th1 cells in the spleens, lungs, and livers in response to E. coli infection, resembling the phenotypes of LPS challenge." (PMID 40510337, 2025).
eosinophilia (1 paper, 2024). "We also show that DOCK2 mice have eosinophilia on a C57BL/6 background whereas previously this was only shown in TH2-prone Balb/c mice." (PMID 38366567, 2024).
Epstein-Barr virus infection (1 paper, 2023). An infection that is caused by Epstein-Barr virus. "Another patient with DOCK2 deficiency developed HLH in the setting of Epstein-Barr virus infection after hematopoietic stem cell transplantation." (PMID 36836791, 2023).
glaucoma (1 paper, 2023). Increased pressure in the eyeball due to obstruction of the outflow of aqueous humor. "Wnt signaling also activates Rac1, Racgap1, Iqgap3, and Dock2 genes in this pathway that were upregulated in three day glaucoma." (PMID 37762022, 2023).
liver cancer (1 paper, 2022). An epithelial or non-epithelial malignant neoplasm that arises from the liver. "According to the median risk score, DOCK2 mutant liver cancer patients with clinical information were divided into the high-risk group and low-risk group." (PMID 35620462, 2022). "Survival analysis was conducted based on the DOCK2 mutation data and prognostic information of liver cancer patients, and the results revealed that the mutation of DOCK2 had an essential impact on the prognosis and survival of patients." (PMID 35620462, 2022). "Then, univariate Cox analysis and multivariate Cox analysis were performed based on the age, gender, clinical stage, tumor stage, and risk score of DOCK2 mutant liver cancer patients, thus building a clinical prediction model, the efficacy of which in 28 DOCK2 mutant samples was 85.8%." (PMID 35620462, 2022). "As liver cancer is considered an immunogenic tumor, the relationship between the expression of DOCK2, SCTR, TANC1, ALKBH7, FREM2, and GNG4 and the levels of immune cells and stromal cells was assessed." (PMID 35620462, 2022). "Furthermore, in order to comprehensively evaluate the roles of the targets in DOCK2-MUT and DOCK2-WT in liver cancer, the GSVA was conducted." (PMID 35620462, 2022).
liver cirrhosis (1 paper, 2022). "The two remaining significant subclusters at lower JI (0.4 and 0.14) contribute with other biologically relevant connectors such as MAPK, a putative regulator of the immune response in liver cirrhosis and DOCK2 involved in immune inflammatory processes such as lymphocyte activation and migration." (PMID 36458021, 2022).
lupus (1 paper, 2014). "We have therefore here evaluated the effect of IRF5-deficiency in the MRL/lpr mouse lupus model in the absence of the DOCK2 mutation." (PMID 25076492, 2014). "In summary, we have shown that IRF5 plays an important role in the development of disease in the MRL/lpr mouse model of lupus in the absence of the DOCK2 mutation and that IRF5 is required for the transition from mature B cells to plasma cells." (PMID 25076492, 2014). "As DOCK2 regulates lymphocyte trafficking and Toll-like receptor signaling, this raised the possibility that some of the protective effects attributed to IRF5 deficiency in the mouse lupus models may instead have been due to DOCK2 deficiency." (PMID 25076492, 2014). "The effect of IRF5 deficiency in the MRL/lpr lupus model was reported before the DOCK2 mutation was discovered and no information is available as to whether the DOCK2 mutation was present in the experimental mice in that study." (PMID 25076492, 2014).